LINC01377 (long independently transcribed non-coding RNA 1377)
Gene: Long non-coding RNA gene on chromosome 5 (3,177,792 to 3,181,489, forward strand). Ensembl gene ENSG00000249808.
Diseases named in the same sentence as LINC01377 in open-access papers:
LINC01377 is named in the same sentence as 1 disease in open-access papers, as found by Europe PMC text mining. Sharing a sentence is not in itself a finding about the gene and the disease.
LINC01377 shares sentences with these, for which no sentence is quoted: cancer (1 paper).